PTH (parathyroid hormone)
Diseases named in the same sentence as PTH in open-access papers (continued):
Sharing a sentence is not in itself a finding about the gene and the disease.
Hypercalcemia (continued). "Systematic literature review revealed ectopic PTH production by malignancies as an extremely rare cause of hypercalcemia and that most cases were initially misdiagnosed as primary hyperparathyroidism and underwent unnecessary surgical neck exploration in almost all cases." (PMID 39703837, 2024). "Ectopic production of PTH is another possible cause of malignancy-associated hypercalcemia; however, the patient's suppressed PTH level (<2 pg/mL) makes this hypothesis unlikely." (PMID 39677199, 2024). "While PTH regulates serum calcium and phosphate levels, PTHrP, a hormone in the PTH family, has crucial developmental and physiological roles and is a primary cause of malignancy-related hypercalcemia." (PMID 39028425, 2024). "Elevated PTH concentration is an extremely rare cause of hypercalcemia in malignant tumors." (PMID 38920679, 2024). "From the laboratory evaluation, the following stand out: mild hypercalcemia (calcium correction for albumin of 2.8 mmol/L), hypophosphatemia (0.58 mmol/L), a significant increase of alkaline phosphatase (2176 U/L) and PTH (2410 pg/mL), and vitamin D deficiency (6.94 ng/mL)." (PMID 39463573, 2024). "It is also associated with extremely high levels of serum PTH and hypercalcemia." (PMID 39463573, 2024). "In patients with low PTH, PTHrp, and 1,25-dihydroxyvitamin D, hypercalcemia due to osteolytic metastases may be considered the cause of malignancy-associated hypercalcemia." (PMID 37033238, 2023). "Intoxication, particularly excessive doses of vitamin D, may lead to hypercalcemia, hypercalciuria, an imbalance in bone metabolism, fatigue, diarrhea, dehydration, weight loss, kidney stones, confusion, psychosis, nausea, and parathyroid hormone imbalance." (PMID 37505607, 2023). "Serum phosphorus and other electrolytes should be measured, as hypercalcemia due to PTHrP or PTH may cause hypophosphatemia, hyperchloremia, and mild metabolic alkalosis." (PMID 37033238, 2023). "Additionally, the extended exposure to excessive PTH that develops from parathyroid adenoma or parathyroid hyperplasia in primary hyperparathyroidism causes hypercalcemia, bone loss, and an elevated risk of fracture." (PMID 37711876, 2023). "However, in 15–30% of patients, PTH remains high for >6 months and this can cause persistent hypercalcemia and hypophosphatemia." (PMID 37311769, 2023). "This does not contradict our results: the primary pathogenetic factor of hypertriglyceridemia could be increased PTH, and the association with hypercalcemia in this case is indirect." (PMID 37842310, 2023). "A rare cause of PTH-independent hypercalcemia is described in the present case report." (PMID 37011375, 2023). "Indeed, the relationship between calcium and PTH was strongest in the setting of hypercalcemia, with greater PTH levels begin associated with a greater degree of perturbation in calcium." (PMID 37251673, 2023). "Several studies reported that RT was associated with hypercalcemia, which may be due to RT secreting parathyroid hormone-related peptide (PTH-rP) and easily involving bones." (PMID 37547104, 2023). "Elevated parathyroid hormone (PTH) levels promote bone resorption, calcium (Ca) reabsorption from the tubular tubes, and Ca absorption from the intestinal tract by increasing the production of 1,25-dihydroxycholecalciferol, often causing hypercalcemia." (PMID 35710357, 2022). "The causes of neonatal hypercalcaemia can be classified into high or low PTH disorders." (PMID 33990852, 2022). "Future RCTs could examine whether atorvastatin can treat PTH dependent hypercalcemia due to lithium and other causes." (PMID 36153583, 2022). "PTH may cause both hypertrophy and necrosis by directly affecting the cardiac myocytes, and hypercalcemia may also affect Tp-e and QT durations by electrically shortening the plateau phase of the cardiac action potential and the effective refractory period." (PMID 36161626, 2022).
Hypercalcemia (continued). "While these increases were thought to be related to excess parathyroid hormone, it is known that hypercalcemia is one of the reversible metabolic causes of delirium in patients with advanced cancer for instance, and that treatment of hypercalcemia resulted in symptom control." (PMID 36030220, 2022). "Whether GCM2 variant-induced increased PTH mRNA expression, if present, could then cause increased PTH secretion and potentially contribute to hypercalcemia is possible but remains an area for future studies." (PMID 35038313, 2022). "Parathyroid carcinoma is a rare form of primary hyperparathyroidism that may be associated with PTH dependent hypercalcemia." (PMID 35676731, 2022). "Patients without a diagnosis with frankly elevated PTH greater than or equal to 65 pg/mL may be explained by the fact that clinicians often attribute hypercalcemia to other causes, even in patients with elevated PTH." (PMID 36574247, 2022). "Two groups without a documented diagnosis of PHP were identified as high risk: 20 176 patients (14.9%) with parathyroid hormone greater than or equal to 50 pg/mL and 24 905 patients (18.4%) with no parathyroid hormone level obtained or recorded explanation for hypercalcemia." (PMID 36574247, 2022). "Among its causes, systemic secretion of parathyroid hormone-related protein (PTHrP) and ectopic production of 1,25-dihydroxyvitamin D and parathyroid hormone (PTH) may be considered paraneoplastic causes of hypercalcemia." (PMID 36294693, 2022). "The patients in our report improved symptomatically following treatment with calcium and an active vitamin D analogue (alphacalcidol), which normalized serum calcium and phosphorus levels, although they eventually developed hypercalcemia in association with progressive increase in serum PTH levels." (PMID 35497370, 2022). "Immediate-release calcifediol reduces parathyroid hormone by clinically meaningful amounts (≥ 30%) only when administered at doses that both raise serum 25(OH)D to supra-physiological levels (> 100 ng/mL) and increase the risk of hypercalcaemia." (PMID 34626363, 2022). "The first of the study patients with AHH was a 76-year-old man with a chief complaint of appetite loss and in whom PTH-dependent hypercalcemia with hypocalciuria was detected (cCa, 13.8 mg/dL; iP, 1.9 mg/dL; Cre, 0.82 mg/dL; intact PTH, 60 pg/mL; and FECa of 0.32%)." (PMID 36099030, 2022). "In more than 90% of cases, the presence of a parathyroid malignancy is associated with a consistent secretion of PTH, causing hypercalcemia and potentially all clinical conditions due to primary hyperparathyroidism, although non-secreting parathyroid carcinoma can occur." (PMID 35872978, 2022). "Parathyroid carcinoma is an uncommon cause of PTH-dependent hypercalcemia." (PMID 36284286, 2022). "This may in turn suppress PTH in the fetus and may explain why newborns of mothers with CYP24A1 mutations are at risk of both, hypercalcemia due to transfer of calcium from the mother during pregnancy and of hypocalcemia due to suppression of PTH." (PMID 35745247, 2022). "Therefore, it emerges as a spectrum of PTH-related disorders associated with hypercalciuria and with serum calcium levels ranging from normocalcemia to hypercalcemia." (PMID 34977081, 2021). "The surgical excision of hyper-functioning parathyroid tissue (parathyroidectomy; PTX) is indicated to prevent clinical complications due to prolonged elevated levels of PTH and calcium, such as bone loss, nephrolithiasis and hypercalcemia-induced neuromuscular, heart and brain alterations." (PMID 34440663, 2021). "The causes of hypercalcaemia associated with appropriately suppressed PTH secretion are extensive." (PMID 33614549, 2021). "PTH related hypercalcemia is most commonly caused by primary hyperparathyroidism, when adenomas are most often eutopic, i.e., have parathyroid location when imaged with 99mTc-MIBI- SPECT/CT, but several adenomas with ectopic locations have been published in the literature." (PMID 34829354, 2021).
Hypercalcemia (continued). "Thus, patients with recessive mutations presented with mild hypercalcemia, hypophosphatemia, low intact PTH levels, hypercalciuria, bone dysplasia, kidney stones, bowing and osteopenia." (PMID 33536578, 2021). "Moreover, we have demonstrated that cinacalcet has a rapid effect in decreasing plasma PTH concentrations and in alleviating the hypercalcaemia associated with FHH3." (PMID 33729479, 2021). "The vast majority of parathyroid adenomas are functioning due to an altered set point in terms of calcium sensing mechanisms, and the ensuing parathyroid hormone (PTH) secretion leads to hypercalcemia that may cause diverse symptoms in the afflicted patient." (PMID 33269427, 2021). "Exposure to higher than normal levels of PTH can cause various hypercalcemia-related clinical manifestations, with an incidence of maternal complications of approximately 67% and that of fetal or neonatal complications of approximately 80%, leading to 30% fetal or neonatal deaths." (PMID 34420520, 2021). "Due to low bone mineralization, and unlike most types of rickets/osteomalacia, common metabolic abnormalities such as hypercalcemia, hyperphosphatemia, low levels of parathyroid hormone (PTH), and elevated hypercalciuria can occur causing nephrocalcinosis and kidney involvement." (PMID 33919113, 2021). "This, coupled with increased PTH and hypercalcemia, may especially compromise high-risk populations such as those of African ancestry who are disproportionately diagnosed with more aggressive tumors and, consequently, higher cancer mortality rates." (PMID 34357109, 2021). "In MEN1 patients, PTX is strongly suggested in the presence of increased PTH and hypercalcemia to prevent/reduce the early-onset bone mass loss and grant, in young patients, the achievement of the bone mass peak; routine monitoring of bone metabolism and bone mass should start from adolescence." (PMID 34440663, 2021). "However, there are a few reported cases of non-PTH-dependent hypercalcemia associated with acromegaly." (PMID 33933067, 2021). "An altered level of vitamin D and hypercalcemia causes a suppression of parathyroid hormone." (PMID 31851454, 2020). "The effect of denosumab on RANKL signaling, inhibition of PTH-driven bone resorption and associated reduction of serum calcium levels makes it a useful tool to control severe hypercalcemia in patients with PHPT before surgery or if surgery is contraindicated for some reasons." (PMID 33112830, 2020). "However, an outstanding question has been how hypercalcemia causes the suppression of PTH production and secretion." (PMID 32213715, 2020). "Hypercalcemia with normal PTH levels is very unusual and can lead to diagnostic difficulties." (PMID 31074404, 2019). "In addition, it must also be noted that RK + SF rats showed over-suppression of PTH and hypercalcemia, the important risk factors for adynamic bone disease and cardiovascular events, respectively." (PMID 30741979, 2019). "The differential diagnosis of neonatal hypercalcaemia includes idiopathic infantile hypercalcaemia, William syndrome, subcutaneous fat necrosis, vitamin D intoxication and hypophosphatasia; all of which are associated with low PTH levels." (PMID 32120468, 2019). "Occasional case studies indicate that octreotide might affect PTH-associated hypercalcemia and reduce the urinary calcium output in primary hyperparathyroidism." (PMID 31336364, 2019). "Hypercalcemia as a result of excessive secretion of PTH is considered as the hallmark of PHPT." (PMID 31102836, 2019). "FGF23 also interacts with serum PTH, although the association is less clear and may be based on hypercalcemia." (PMID 31615041, 2019). "Before age 8, almost all cases of PTH-dependent hypercalcemia are caused by familial hypocalciuric hypercalcemia (mostly from mutation in CASR, AP2S1, or GNA11) or by neonatal severe primary hyperparathyroidism, both of which have near 100% penetrance for hypercalcemia already in the neonate." (PMID 30065698, 2018).
Hypercalcemia (continued). "It is practical to recognize circulating levels of PTH initially and decide whether the cause of hypercalcemia is PTH-dependent or PTH-independent." (PMID 28443817, 2017). "In this case, in the setting of pancreatic NET, hypercalcemia associated with hypophosphatemia and suppressed PTH levels were highly likely due to PTH-rp secretion, although serum PTH-rp levels could not be measured." (PMID 28977163, 2017). "Persistently elevated PTH and hypercalcaemia are the diagnostic markers of PHPT3." (PMID 28687737, 2017). "A practical approach to hypercalcemia in children requires measurement of accompanying levels of PTH to determine whether the cause is PTH-dependent or PTH-independent." (PMID 28443817, 2017). "Although hypercalcemia often leads to decreased serum phosphate levels, decreased PTH levels may cause increases in the reabsorption of phosphate in the kidney tubules." (PMID 28121960, 2017). "This form is associated with a more severe FHH variant that may lead to symptomatic hypercalcaemia with hypophosphoraemia and an increase of PTH with age, low bone mineral density and cognitive dysfunction.." (PMID 28122587, 2017). "Causes of hypercalcemia of malignancy include parathyroid hormone-related peptide (PTHrP) secretion, local osteolysis, calcitriol production and ectopic parathyroid hormone (PTH) secretion." (PMID 26998187, 2016). "Often, this serum hypercalcemia is due to increased parathyroid hormone production by the tumor, but it is still unclear whether the mechanism of hypercalcemia in these patients is related to the SWI/SNF mutations." (PMID 26646792, 2016). "All subjects with normal PTH levels by both assays had other causes of hypercalcemia excluded." (PMID 27812604, 2016). "A reversal of the factors favoring mineralization (vitamin D therapy and low phosphate clearance) allowed for dissolution of the calcium deposits, which we hypothesize caused transient, severe parathyroid hormone (PTH)-independent hypercalcemia." (PMID 27683096, 2016). "However, the 10% of PC that are associated with hypercalcaemia (functioning cysts) demonstrate a male preponderance and invariably contain elevated C-terminal PTH (C-PTH) levels." (PMID 26064758, 2015). "Both low and high blood PTH levels and 1,25(OH)D (1,25 hydroxy-vitamin D) can cause hypercalcaemia." (PMID 25543193, 2015). "The detection of hypercalcemia and elevated PTH levels was diagnostic of PHPT." (PMID 25631825, 2015). "If the hypercalcemia persists after resection of an adenoma, then the differential diagnosis would depend on whether the hypercalcemia is associated with a relatively high or a low PTH." (PMID 24716007, 2014). "Parathyroid carcinoma is a rare cause of PTH-related hypercalcemia." (PMID 24829837, 2014). "Although one cannot directly compare a drug dosage for humans to the dosage in animals or vise versa, it is possible that the PTH dosage of 80 μg/kg may cause hypercalcemia in some patients." (PMID 24503654, 2014). "With a low PTH, hypercalcemia must depend on other causes that have to be sought." (PMID 24716007, 2014). "Persistence of hypercalcemia after removal of the causal lesion should prompt a thorough workup for another source based on whether the offending agent is PTH, PTHrP, or Vitamin D." (PMID 24716007, 2014). "However, the patient's PTH levels were normal and hindered diagnosis; hence it was necessary to investigate all possible causes of hypercalcemia." (PMID 25003934, 2014). "Hypercalcemia can be divided into PTH-mediated and PTH-independent variants." (PMID 24716007, 2014). "Some studies suggest that intermittent administration is associated with a lower incidence of hypercalcemia and may suppress PTH with more efficacy than daily administration of activated vitamin D." (PMID 24495277, 2014).
Hypercalcemia (continued). "In case of lithium treatment, a decrease in parathyroid sensitivity to calcium has been suggested as the principal mechanism of action for the increased secretion of parathyroid hormone resulting in hypercalcemia, the biochemical hallmark of primary hyperparathyroidism." (PMID 25505674, 2013). "Similarly, hypercalcemia and uremia cause vascular calcification by active processes suggesting the importance of strict management of uremia, serum minerals and PTH in dialysis patients." (PMID 23940515, 2013). "PTH assays can reliably distinguish PHPT from other causes of hypercalcemia." (PMID 24106573, 2013). "Like PTH, PTHrP causes hypercalcemia by promoting bone resorption and decreasing calcium excretion." (PMID 23476667, 2013). "A DOPPS study also evaluated combinations of serum parameters of mineral metabolism, but reached slightly different conclusions, with elevated serum PTH (>300 pg/mL) and hypercalcemia (>10 mg/dL) being associated with increased mortality risk even under normal serum phosphorus levels." (PMID 23525083, 2013). "An infant with a maternally inherited mutated allele will have a more benign clinical picture than an infant with a paternally inherited mutated allele because the resulting mild maternal hypercalcemia helps to activate the mutated fetal CaSR and inhibit expression PTH secretion." (PMID 22620673, 2012). "There are objections against the hypothesis that hypercalcaemia per se or PTH causes enhanced cellular influx of calcium and raised cytosolic calcium." (PMID 21423544, 2011). "Therefore, a diagnosis of milk-alkali syndrome was considered due to the combination of excess alkali ingestion, hypercalcemia, renal failure, associated metabolic alkalosis and exclusion of other causes of PTH-independent hypercalcemia." (PMID 21455429, 2011). "Our results indicate that reductions in hypercalcemia reduce the early lethality of CaR–deficient mice and that deletion of PTH in patients with NSHPT may normalize skeletal growth and development." (PMID 21966280, 2011). "Therefore, a double-knockout model was established by crossing the PTH-deficient with the CaR–deficient mice to correct the severe hyperparathyroidism, hypercalcemia and hypophosphatemia observed in the homozygous CaR–deficient mice." (PMID 21966280, 2011). "Continuous exposure to PTH increases bone resorption, hypercalcemia and bone loss." (PMID 20305819, 2010). "However, intermittent administered PTH also stimulates bone resorption and therefore can cause hypercalcemia, which can be inhibited by co-administration of PTH and antiresorptives." (PMID 19747396, 2009). "Parathyroid carcinoma is a rare malignancy and is an uncommon cause of PTH-dependent hypercalcemia." (PMID 16569241, 2006). "PTH stimulation of bone resorption by OMGCs suggests that PTH or a PTH-like protein, may be involved in the bone resorption and consequent hypercalcaemia associated with metastatic breast cancer." (PMID 2713238, 1989). "Biological tests revealed corrected hypercalcemia at 2.77 mmol/L, hypophosphatemia at 0.82 mmol/L, calcemia/phosphoremia ratio is 3.37, elevated alkaline phosphatase up to 30 times the normal level, elevated PTH at 1871 pg/mL, and a deficiency in 25‐hydroxyvitamin D3 (25‐(OH)‐D) at 10.8 ng/mL." (PMID 41568160, 2026). "Prolonged hypercalcemia in hyperthyroid patients may influence parathyroid hormone secretion; in this case, it remains unclear whether the long-standing history of hyperthyroidism is associated with changes in parathyroid hormone levels." (PMID 40224187, 2025). "Moreover, maternal hypocalcemia can lead to fetal parathyroid hyperplasia and related skeletal changes, while maternal hypercalcemia may suppress fetal parathyroid hormone production, causing neonatal hypocalcemia." (PMID 40958864, 2025).